ENSG00000239137
Synonyms: LOC124904795
Gene: Small nucleolar RNA gene on chromosome 19 (55,167,171 to 55,167,274, forward strand). Ensembl gene ENSG00000239137.
Gene Ontology:
Biological process: RNA processing
Cellular component: nucleolus
Homologues: Paralogues in human: SNORD13 (85% identical), SNORD13D (84% identical), SNORD13P1 (84% identical), SNORD13P3 (83% identical), SNORD13E (82% identical).